TF (transferrin)
Diseases named in the same sentence as TF in open-access papers (continued):
Sharing a sentence is not in itself a finding about the gene and the disease.
cancer (continued). "By conjugation with cancer cell targeting biomolecules, such as transferrin, RGD peptide, folate, and gracilaria lemaneiformis polysaccharide, Se NPs could selectively deliver anticancer drugs into cancer cells to achieve enhanced anticancer activity." (PMID 29019267, 2017). "Given the critical role of bZip domain TF families (e.g. AP-1, ATF and CREB) in various cancers, inflammation and developmental processes, concurrent miRNA binding to mRNA regions overlapping these sites (e.g. miR-224-TCF21) may represent an exquisite fine-tuning control of target gene expression." (PMID 24676100, 2014). "A covalent conjugate of artemisinin and transferrin (ART-Tf), an iron transport protein in human, is actively taken up by cancer cells through the transferrin receptor (TfR)-mediated endocytosis pathway, and shows significantly higher anti-cancer activity than unconjugated artemisinin." (PMID 20657468, 2010). "We analyzed the TF regulatory network of HGSOC and found that PRRX1exhibited high specificity and expression levels in the C2 subtype, and its correlation with poor prognosis suggested that it may have played a significant role in the development and progression of cancer." (PMID 39896800, 2024). "Furthermore, transferrin is overexpressed on most cancer cells, and transferrin-targeted RES-Ls may be an effective nanomedicine for the treatment of various cancers, including GBM, even though their biodistribution in vivo and ability to cross the BBB remain unknown." (PMID 37456742, 2023). "In cancer-specific enhancers in A549 cells, there was far less enrichment for both NKX2–1 and FOXA1, with no obvious differences in TF position relative to the center of the peak." (PMID 34922464, 2021). "A study examined the expression of TF and Tn in NAF samples from 25 breasts with cancer and 25 normal breasts." (PMID 32992445, 2020). "For example, transport-related pathways (“Transferrin endocytosis and recycling” and “Passive transport by Aquaporins”) were reproducibly identified in COAD in both the GSE100179 and TCGA patient cohort and not in other cancers." (PMID 36229842, 2022).
infection (294 papers, 2007 to 2026). The state of being infected such as from the introduction of a foreign agent such as serum, vaccine, antigenic substance or organism. "Elemental iron is a critical nutrient for bacterial growth, and various bacterial species express iron transport proteins that compete with transferrin, potentially resulting in an increased risk of infection due to iron overload." (PMID 41231850, 2025). "From the perspective of infection risk, the iron-binding ability of transferrin can limit the access of pathogens to iron." (PMID 40765572, 2025). "The challenge is heightened for pathogenic fungi during infection, as they must compete with the host’s iron-binding proteins like transferrin and lactoferrin, which sequester iron to restrict pathogen growth." (PMID 40391928, 2025). "In conclusion, our data for these TF genes validate AS events and corroborate the idea that pathogenic fungi show different AS patterns in their infection environments." (PMID 41001418, 2025). "The polymorphism of TF proteins is helpful for organisms to adapt to environmental changes and resist pathogen infection." (PMID 36552378, 2022). "Metzger and co-workers (2010) observed that the expression of the transferrin-encoding gene was upregulated up to 71 days post-infection (dpi) in two chinook salmon stocks following R. salmoninarum i.p. infection." (PMID 36138795, 2022). "Although the growth of some pathogens is enhanced in the presence of TF, it can limit infections caused by some pathogens through reducing the iron level in the surrounding environment." (PMID 36552378, 2022). "We believe that Fe3+ sequesters, such as lactoferrin and tissue associated transferrin, will provide an accessible pool of ferric iron because these molecules are evidently upregulated during infection and stress conditions, respectively." (PMID 35308377, 2022). "During infection, vertebrates use the serum protein transferrin to chelate Fe, thereby forming a Fe-deficient environment." (PMID 34017347, 2021). "The data were informative for demonstrating that clinical determinations of TF were highly associated with infection, but we had insufficient data to determine a prevalence of infection associated with re-emergence." (PMID 33861754, 2021). "Cytokine induction seemed to be associated with time post-infection as C7, C12 and to a lesser extent, C15, three of the four best inducers of cytokine release were cloned from TF variants." (PMID 32615983, 2020). "Newborns are especially susceptible to iron overload-related infections due to a less efficient transferrin production." (PMID 32245010, 2020). "The relationship found between higher serum iron levels and transferrin saturation, and a higher infection risk was initially proposed and expected." (PMID 31261772, 2019). "Transferrin saturation above the median value (>32.1%) was associated with a higher infection risk (HR 4.3; 95%CI 1.0–19.69; p = 0.05)." (PMID 31261772, 2019). "New pannus was significantly associated with Ct infection after adjustment for TF (P = 0.009, OR = 3.65 (1.4–9.8))." (PMID 26812948, 2016). "The performance of TF alone as a clinical diagnostic test for Ct infection in these samples was perhaps overinflated by the study design." (PMID 26812948, 2016). "New pannus was independently associated with Ct infection after adjustment for TF (P = 0.009, OR = 3.65 (1.4–9.8))." (PMID 26812948, 2016). "In multivariable logistic regression analysis TF was strongly associated with Ct infection (P = 1.16 x 10−7, OR = 18.17 (6.73–59.5))." (PMID 26812948, 2016). "At the individual level the utility of TF as a marker for infection is highly sensitive to the underlying prevalence of TF." (PMID 27783678, 2016). "It is possible that in a low-prevalence area the sensitivity of TF and new pannus together as a diagnostic tool for Ct infection would be improved relative to TF alone." (PMID 26812948, 2016).
infection (continued). "Our results therefore suggest that many of the commonly up-regulated genes found in the four TF mutants function as positive regulators of disease susceptibility, and that their expression is induced during the course of pathogen infection." (PMID 25830627, 2015). "Older formulations, high-dose IV iron therapy and various underlying conditions may elevate infection susceptibility due to increased levels of non-transferrin-bound iron." (PMID 41881665, 2026). "We found that bacterial products including LPS, LTA, and bacterial DNA from both pathogenic and probiotic bacteria up-regulated transferrin expression, suggesting that microbe commensalism and/or infections have the ability to up-regulate transferrin expression." (PMID 38274126, 2024). "This may be related to an increase in plasma non-transferrin-bound iron (NTBI) leading to susceptibility to infection.21pancreas, and other organs." (PMID 39092027, 2024). "In these districts, it is unclear whether the classification based on TF prevalence was overestimated due to sampling error or whether the observed follicles leading to diagnoses of TF were caused by another pathogen or ocular Ct infection." (PMID 39406720, 2024). "In our study, we observed that serum transferrin level was positively correlated with serum albumin and hemoglobin, which suggested that patients with lower transferrin had poor nutritional status and, in turn, they were more susceptible to infection." (PMID 32922172, 2020). "Our results show that upon disruption of target genes, protein trafficking to lysosomes and recycling of transferrin to the plasma membrane is reduced: this suggests that endosomal sorting and recycling to the plasma membrane are closely linked to trans-infection in MDDCs." (PMID 32075937, 2020). "Higher infection risk was associated with higher serum iron and transferrin saturation." (PMID 31261772, 2019). "We base our conclusion on three observations: (i) susceptibility of infection and single particle uptake to disruption of dynamin; (ii) co-packaging and -transport of incoming virions with transferrin; and (iii) detection of rhabdoviral particles within coated pits by electron microscopy." (PMID 27463226, 2016). "New pannus was independently associated with Ct infection after adjustment for TF, suggesting that use of the two clinical signs together might increase the likelihood of detecting Ct positive individuals." (PMID 26812948, 2016). "In this context, a relatively high transferrin saturation in our patient might be an additional risk factor for infection." (PMID 26467000, 2015). "On the other hand, decrease of transferrin levels may lead to pathological free-serum iron levels rendering individuals more susceptible to infection by iron-dependent microorganisms." (PMID 19358702, 2009). "Thus, when ferritin may be higher due to infection or inflammation, greater ferritin thresholds (<100 mcg/L) along with low transferrin saturation (<20%) may have diagnostic value." (PMID 38994175, 2024). "Thus, variations in XRE TF expression may underlie the observed φCbK infection phenotype of skaH insertional mutants." (PMID 37972151, 2023). "Our study provided novel evidence that overexpression of transferrin due to N. ceranae infection could suppress the honey bee’s immune response, thereby making immunodeficient honey bees more susceptible to the disease infection." (PMID 33600478, 2021). "TF is only indirectly associated with infection with the causative agent Chlamydia trachomatis, in part because the clinical signs of trachoma may persist for months after infection has been cleared." (PMID 26489933, 2015). "CONCLUSION: We conclude that future clinical evaluation of the [68Ga]Ga-siderophore approach to infection imaging requires a deeper understanding of the kinetics and thermodynamics of transchelation of 68Ga between the siderophores and transferrin." (PMID 41790228, 2026).
infection (continued). "To assess the response of TF-KO compared with that of TF-WT phagocytes following P. salmonis infection, we performed an in vitro infection assay and monitored the cytopathic effects (CEs) in both cell lines." (PMID 40999544, 2025). "Although it is possible to sustain an infection with N. meningitidis in these mice, since they have been modified to express human transferrin, it is important to remember that the meningococcus is a human pathogen." (PMID 40818988, 2025). "Consistent with broader nutritional immunity strategies, we also found increased expression of transferrin, a known mediator of Fe sequestration during infection." (PMID 39841126, 2025). "Since this time, studies have revealed a poor correlation between Ct infection and TF prevalence in settings where multiple MDA rounds have been administered." (PMID 40067808, 2025). "Although all districts had a TF prevalence greater than 5%, one remained highly endemic, with a high prevalence of TF, infection, and antibodies." (PMID 40067808, 2025). "In clinical liver transplantation patients, those with lower transferrin levels had a higher incidence of postoperative infections." (PMID 40765572, 2025). "In vitro infection assays revealed that, compared with wild-type (TF-WT) cells, TF-KO cells presented reduced cytopathic effects, decreased formation of P. salmonis-containing vacuoles (PCVs), and improved viability." (PMID 40999544, 2025). "This allowed us to compare the performance of the mutant (TF-KO) and wild-type (TF-WT) cell lines during in vitro infection with P. salmonis." (PMID 40999544, 2025). "Transferrin appears to be expressed under settings of oxidative stress, in addition to being upregulated by pathogen infection." (PMID 40632758, 2025). "In our enrichment analysis of KEGG biological pathways, the significant pathways enriched by the two regulons are heavily dominated by immune response to inflammation and infection suggesting strong immunity-related functional involvement of the two TF genes." (PMID 38397203, 2024). "Our analysis revealed a complex relationship between different time points after infection and the transcriptional responses of other resistance-related genes, implying that PK and TF can influence both of different sesame varieties." (PMID 38262910, 2024). "Another mechanism connecting iron and high phosphate in infection is through increased circulating non-transferrin-bound iron (NTBI)." (PMID 39666728, 2024). "It is also possible that low serum iron and transferrin saturation represent infection and inflammation." (PMID 39464186, 2024). "In conclusion, our findings revealed that immune activation due to microbe infection results in iron withdrawal, while both infection and iron withdrawal promote host transferrin expression." (PMID 38274126, 2024). "Iron is an essential element for the survival of bacterial pathogens inside the host during infection as they face a shortage of free iron due to the binding of this metal ion to transferrin, ferritin, and lactoferrin." (PMID 37153161, 2023). "have shown that transferrin levels were decreased during severe infection in comparison to boosted levels of ferritin, this corroborates our ferritin levels observations." (PMID 36776891, 2023). "In agreement with the high intracellular survival rate over the time of infection, we found that intracellular B. parapertussis has access to nutrients from the recycling pathway, as determined by bacterial colocalization with transferrin." (PMID 38011105, 2023). "Other iron indicators can be used to validate the importance of iron, especially transferrin as it`s levels can be also affected during infection or inflammation." (PMID 36776891, 2023). "While two rounds of MDA had a moderate impact on TF and antibody prevalence in each EU, there was a >8-fold decrease in infection prevalence in Tarawa, from 27.4% at baseline to 3.3% at TIS." (PMID 37418501, 2023).
infection (continued). "The combined visual inspection of Rab11 distribution in mock and infected cells with transferrin (Tf) recycling assays allows determining the fate of Rab11a endosomes in infection." (PMID 37983294, 2023). "Each TF mutant was paired with the WT strain in the infection to better control for day-to-day variation." (PMID 36847358, 2023). "Second, as a consequence of such competition, we have shown that transferrin (Tf) recycling is reduced throughout infection." (PMID 37983294, 2023). "A similar expression pattern of these TF gene families was previously observed after infection by P. parasitica in Nicotiana benthamiana and A. thaliana, both of which are susceptible host plants." (PMID 37446029, 2023). "During infection, the content of iron storage proteins in the human host increases, and free iron ions bind to iron‐transporters (e.g., transferrin) that proactively maintain a lower serum iron level to limit iron uptake by pathogens." (PMID 37607533, 2023). "During infection, pathogens encounter an almost iron-free environment as the available iron is tightly sequestered by host proteins, e.g., hemoglobin, transferrin, lactoferrin, and ferritin." (PMID 37388440, 2023). "The level of serum transferrin varies in response to stress conditions and infection, and as such is considered a potential biomarker for acute phase response in vertebrates." (PMID 37268947, 2023). "Gallium-67 is a radioactive atom that binds to transferrin and therefore will locally accumulate in areas of increased perfusion and vascular permeability, such as areas of active infection." (PMID 37483708, 2023). "Iron is essential for bacterial growth; however, mammals sequester iron using the iron-binding proteins transferrin and lactoferrin, which prevent infection through nutrient restriction, a concept known as nutritional immunity." (PMID 36946760, 2023). "During any infection, the host immune response can limit iron availability by complexing iron within ferritin or by removing iron with transport proteins such as transferrin (Tf) and lactoferrin (Lf), which are then stored in the form of heme (2, –, 4)." (PMID 36749044, 2023). "During the acute infection or the inflammatory phase of chronic disease, serum iron and ferritin are increased, whereas transferrin is decreased." (PMID 36422508, 2022). "As ompA variation was important in Ct phylogeny and heterogeneity in TF profiles, we further investigated the geographical distribution of ompA serovars and their relationship to levels of Ct infection and TF." (PMID 33034349, 2022). "Then, the wild-type (WT) and dominant-negative mutant plasmids (DN) of EPS15 were transfected into cells, followed by incubation with transferrin or infection with PDCoV 24 h later." (PMID 35336903, 2022). "Ct infection and TI prevalence were significantly higher with increasing ompA diversity; a similar trend was found for TF prevalence." (PMID 33034349, 2022). "Serum transferrin concentration in vertebrates varies with the infectivity of the microorganism, closely reflecting stress conditions or infection and hence considered as an important biomarker for acute phase response." (PMID 36119096, 2022). "Amongst 1–9-year-olds, the prevalence of TF and serological positivity increased with age, while the prevalence of infection remained stable." (PMID 35439248, 2022). "During infection, K. pneumoniae produces siderophores that can chelate iron, markedly decrease transferrin as well as lactoferrin, and generate a soluble iron complex that can be actively transported into the bacteria." (PMID 36439210, 2022). "Of these, ten focused on TF only, while two examined TT only, one looked at both TF and TT, and one included both a measure of TF and ocular Ct infection." (PMID 35395003, 2022).